TINAGL1 (tubulointerstitial nephritis antigen like 1)
Description:
May be implicated in the adrenocortical zonation and in mechanisms for repressing the CYP11B1 gene expression in adrenocortical cells. This is a non catalytic peptidase C1 family protein (By similarity).
Synonyms: LCN7; P3ECSL; LIECG3; ARG1; TINAGRP
Tractability: Antibody: UniProt places it where antibodies can reach, with high confidence; UniProt predicts a signal peptide or a membrane-spanning region; its Gene Ontology location is reachable by antibodies, with medium confidence.
Gene: Protein-coding gene on chromosome 1 (31,576,485 to 31,587,689, forward strand). Ensembl gene ENSG00000142910.
Subcellular location: Secreted
Gene Ontology:
Molecular function: cysteine-type peptidase activity; protein binding; extracellular matrix structural constituent; laminin binding
Biological process: proteolysis; endosomal transport
Cellular component: extracellular exosome; extracellular matrix; extracellular region; lysosome; cytoplasm
Genetic constraint (gnomAD): Loss-of-function variants: 35 observed, 58.44 expected, observed/expected ratio (o/e) 0.6, 90% interval 0.46 to 0.79. The upper end of that interval is the gene's LOEUF score, 0.79, which puts it in group 3 of 6, group 1 being the genes least tolerant of losing a copy. Missense variants: 516 observed, 632.67 expected, observed/expected ratio (o/e) 0.82, 90% interval 0.76 to 0.88. Synonymous variants: 221 observed, 238.63 expected, observed/expected ratio (o/e) 0.93, 90% interval 0.83 to 1.03.
Homologues: Orthologues: chimpanzee TINAGL1 (100% identical), macaque SERINC2 (99% identical), dog TINAGL1 (93% identical), pig TINAGL1 (93% identical), rabbit TINAGL1 (92% identical), mouse Tinagl1 (89% identical), rat Tinagl1 (88% identical), guinea pig TINAGL1 (87% identical), tropical clawed frog tinagl1 (64% identical), Caenorhabditis elegans cpr-2 (19% identical), Caenorhabditis elegans cpr-5 (19% identical), Caenorhabditis elegans cpr-4 (18% identical), and 11 more. Paralogues in human: TINAG (46% identical), CTSC (22% identical), CTSB (20% identical), CTSZ (19% identical), CTSH (16% identical), CTSV (15% identical), CTSL (15% identical), CTSS (15% identical), CTSK (15% identical), CTSW (14% identical), CTSO (14% identical), CTSF (13% identical).
Diseases named in the same sentence as TINAGL1 in open-access papers:
TINAGL1 is named in the same sentence as 27 diseases in open-access papers, as found by Europe PMC text mining. Sharing a sentence is not in itself a finding about the gene and the disease. The quoted sentences say what the papers report.
triple-negative breast carcinoma (6 papers, 2022 to 2024). An invasive breast carcinoma which is negative for expression of estrogen receptor (ER), progesterone receptor (PR), and human epidermal growth factor receptor 2 (HER2). "In contrast, another study that also focused on the role of TINAGL1 in cancer metastasis showed lower TINAGL1 expression correlates with advanced triple-negative breast cancer tumor stages, reduced disease-free survival, and distant metastasis-free survival." (PMID 38637790, 2024). "Public transcriptome data of patients with triple-negative breast cancer indicated that up-regulation of TINAGL1 was significantly correlated with better prognosis." (PMID 38355577, 2024). "From a functional point of view, TINAGL1 is one of the most interesting up-regulated genes, since the corresponding protein-product suppresses the progression and diffusion of triple-negative breast-cancer via inhibition of the FAK and EGFR signaling pathways." (PMID 37951921, 2023). "TINAGL1 is largely unstudied in the context of glioma but suppresses triple-negative breast cancer progression and metastasis." (PMID 35198102, 2022). "However, Tinagl1 suppresses tumor progression and metastasis by inhibiting integrin/FAK and EGFR downstream signaling pathways in triple-negative breast cancer." (PMID 38355577, 2024). "TINAGL1 was defined as a competitive inhibitor for fibronectin-induced activation of FAK or EGFR, and consequently suppressed tumor progression in mouse models with triple-negative breast cancer." (PMID 38355577, 2024). "Furthermore, integrin α5β1 binding to the secreted protein Tubulointerstitial nephritis antigen-like 1 (Tinagl1), which also involves αvβ1 and epidermal growth factor receptor (EGFR), results in suppressing triple-negative breast cancer progression and metastasis." (PMID 37681100, 2023). "Furthermore, recombinant human tubulointerstitial nephritis antigen-like protein 1 (Tinagl1) has been found to bind to EGFR, thereby inhibiting the progression and metastasis of triple negative breast cancer (TNBC), suggesting that Tinagl1 may act as an effective therapeutic agent for TNBC." (PMID 39796003, 2024).
gastric cancer (4 papers, 2021 to 2025). A primary or metastatic malignant neoplasm involving the stomach. "In gastric cancer, upregulated TINAGL1 enhances the expression of matrix metalloproteinases (MMPs), especially MMP2, via the JNK signaling pathway and promotes tumor progression and metastasis." (PMID 38355577, 2024). "TINAGL1 has been suggested as a potential therapeutic target to suppress metastasis in liver, lung, and gastric cancers." (PMID 38355577, 2024). "In particular, a recent study suggested that TINAGL1 increases expression of MMPs in gastric cancer, and promotes the proliferation and migration of gastric cancer cells." (PMID 38355577, 2024). "A final and significant outcome of our study is the identification of a restricted number of genes which are up-regulated (IRF1, CTSS, PSMB10, CYP26B1, DHRS3 and TINAGL1) and down-regulated (AHNAK2) by ATRA in all the retinoid-sensitive gastric-cancer cell-lines considered." (PMID 37951921, 2023). "Five genes, e.g., DGAT2, JAKMIP1, KRT7, PGLYRP1, and TINAGL1, showed very low correlation coefficient and/or insignificant p-values, suggesting they might not be regulated by KLF5 in human gastric cancer." (PMID 33923166, 2021).
breast carcinoma (3 papers, 2022 to 2025). "TINAGL1, previously established as closely linked to wound healing and implicated in the metastasis of breast cancer, has now been identified in our research as significantly upregulated in the MAT of Crohn's Disease patients." (PMID 38750695, 2025).
hepatocellular carcinoma (2 papers, 2024 to 2025). A malignant tumor that arises from hepatocytes. "Overexpression of TINAGL1 in the liver triggers and exacerbates liver fibrosis, and xenotransplantation of HCV-eradicated Huh7.5 cells leads to a higher risk of hepatocellular carcinoma." (PMID 39781468, 2025).
Tubulointerstitial nephritis (2 papers, 2015 to 2019). "Tubulointerstitial nephritis antigen-like precursor (TINAGL1), was linked to complement proteins, complement C3 (C3) and complement factor H (CFH) in a separate cluster." (PMID 26083627, 2015). "The function in the endometrium of some of these genes has been described in other species, such as for tubulointerstitial nephritis antigen-like 1 (TINAGL1) in mice, where it is markedly expressed in postimplantation decidual endometrium and interacting with integrins." (PMID 31752681, 2019).
COVID-19 (1 paper, 2021). A disease caused by infection with severe acute respiratory syndrome coronavirus 2. "Two examples of this include the proteins ectonucleoside triphosphate diphosphohydrolase 5 (ENTPD5) and tubulointerstitial nephritis antigen like 1 (TINAGL1), which have both been associated with COVID-19 severity." (PMID 34844191, 2021).
Crohn disease (1 paper, 2025). A gastrointestinal disorder characterized by chronic inflammation involving all layers of the intestinal wall, noncaseating granulomas affecting the intestinal wall and regional lymph nodes, and transmural fibrosis. "This marks a pioneering step in associating TINAGL1 with the aggravation of intestinal fibrosis in Crohn's Disease." (PMID 38750695, 2025). "In our investigation of TINAGL1′s role in intestinal fibrosis, particularly in Crohn's Disease, we acknowledge inherent limitations." (PMID 38750695, 2025). "In the dynamic landscape of gastrointestinal disease research, our findings about TINAGL1′s role in Crohn's Disease offer a fresh perspective, particularly in understanding intestinal fibrosis." (PMID 38750695, 2025). "Elevated TINAGL1 levels in exosomes from mesenteric adipose tissue (MAT) significantly influence Crohn's Disease progression." (PMID 38750695, 2025). "By elucidating the role of TINAGL1, predominantly found in mesenteric adipose tissue-derived exosomes of Crohn's Disease patients, we have identified a novel pathway contributing to intestinal fibrosis." (PMID 38750695, 2025). "While the role of TINAGL1 in wound healing and general fibrogenesis has been recognized, its specific impact on intestinal fibrosis, particularly within the context of Crohn's Disease, remains largely uncharted." (PMID 38750695, 2025). "Although its role in general fibrosis has been explored, the specific function of TINAGL1 in the context of intestinal fibrosis, particularly in diseases such as Crohn's Disease, remains largely unexplored." (PMID 38750695, 2025). "Our study unveils pivotal insights into the role of TINAGL1 in the pathogenesis of intestinal fibrosis, particularly focusing on Crohn's Disease." (PMID 38750695, 2025). "We discovered that TINAGL1, enriched in mesenteric adipose tissue-derived exosomes from Crohn's Disease patients, significantly influences fibrogenesis." (PMID 38750695, 2025). "The fibrotic complications in Crohn's Disease present a substantial challenge, and our research suggests that targeting TINAGL1 could offer a new approach to treatment." (PMID 38750695, 2025). "Thus, our study not only deepens the understanding of fibrotic processes in Crohn's Disease but also identifies a potential therapeutic target in TINAGL1." (PMID 38750695, 2025). "Clinical trials focusing on TINAGL1 modulation could also be pivotal in translating these findings into therapeutic interventions for fibrosis in Crohn's Disease and beyond." (PMID 38750695, 2025). "Targeting TINAGL1 or its pathways could offer new strategies for managing and treating the fibrotic complications frequently observed in Crohn's Disease.Furthermore, the implications of our study extend beyond Crohn's Disease." (PMID 38750695, 2025). "•TINAGL1-SMAD4 Interaction: We demonstrate a significant interaction between TINAGL1 and the transcription factor SMAD4, highlighting a previously unexplored pathway in fibrogenesis, with implications for the exacerbation of Crohn's Disease." (PMID 38750695, 2025). "•Novel Insights into Fibrogenesis: Our study reveals the critical role of TINAGL1, enriched in mesenteric adipose tissue (MAT)-derived exosomes, in promoting intestinal fibrosis in Crohn's Disease." (PMID 38750695, 2025).
liver fibrosis (1 paper, 2025). "These clues strongly suggest that TINAGL1 may serve as a potential diagnostic marker for liver fibrosis in patients." (PMID 39781468, 2025). "In this study, we demonstrated for the first time the correlation and mechanism between TINAGL1 and liver fibrosis in patients and mice and at the cellular level." (PMID 39781468, 2025). "Conversely, knockdown of TINAGL1 expression prevents and attenuates the progression of liver fibrosis in mice." (PMID 39781468, 2025). "In summary, this present study uncovered an important role for TINAGL1 in liver fibrosis after HCV elimination by DAAs." (PMID 39781468, 2025). "The results showed that the expression of TINAGL1 was markedly increased in the liver of mouse models with liver fibrosis induced by diethylnitrosamine (DEN) and carbon tetrachloride (CCl4), which histopathology was shown in our previous references." (PMID 39781468, 2025). "Furthermore, TINAGL1 was significantly increased in the livers of patients with metabolic dysfunction associated fatty liver disease (MAFLD), especially with liver fibrosis, as shown by immunohistochemistry (IHC) staining." (PMID 39781468, 2025). "Then, we evaluated whether targeted silencing of TINAGL1 has a therapeutic effect on liver fibrosis." (PMID 39781468, 2025). "To evaluate whether the expression of TINAGL1 was related to liver fibrosis, we detected the expression of TINAGL1 in vivo." (PMID 39781468, 2025). "Here, we found that tubulointerstitial nephritis antigen-like 1 (TINAGL1) is significantly increased in HCV-infected hepatocytes and in the liver of patients with liver fibrosis, and that higher TINAGL1 expression persists in HCV-eradicated hepatocytes after treatment with DAAs." (PMID 39781468, 2025). "In this work, we found that knockdown of TINAGL1 by the AAV8-vector has significant preventive and therapeutic effects on liver fibrosis in mice, highlighting the potential of TINAGL1 as an innovative therapeutic target for the development of new drugs for the treatment of liver fibrosis." (PMID 39781468, 2025). "Taken together, our findings suggest that inhibition of TINAGL1 may be of potential value for the treatment of liver fibrosis." (PMID 39781468, 2025). "Knockdown of TINAGL1 produces preventive and therapeutic effects on liver fibrosis in mice." (PMID 39781468, 2025). "Overexpression of TINAGL1 initiates and exacerbates liver fibrosis in mice." (PMID 39781468, 2025). "Based on our evidence that TINAGL1 is a profibrotic factor for liver fibrosis, we first evaluated whether targeted silencing of TINAGL1 prevents the progression of liver fibrosis." (PMID 39781468, 2025). "Our findings provide new insights into liver fibrosis after virological cure and suggest that targeting TINAGL1 may be a therapeutic potential for the treatment of liver fibrosis." (PMID 39781468, 2025). "This study highlights that TINAGL1 is a new factor contributing to liver fibrosis after injury, including but not limited to HCV infection, even after virological cure by DAAs, and emphasizes the therapeutic potential of TINAGL1 as an innovative target for the treatment of liver fibrosis." (PMID 39781468, 2025). "Therefore, our results highlight that TINAGL1 is a new profibrotic factor in the liver, even after cure with DAA-based therapy, and that targeting TINAGL1 may be an innovative strategy for the treatment of liver fibrosis, especially in the post-antiviral era." (PMID 39781468, 2025). "Here, we found that TINAGL1 is significantly increased in HCV-infected and HCV-eradicated hepatocytes, as well as in the liver of mouse models and patients with liver fibrosis." (PMID 39781468, 2025). "However, we found that the change of TINAGL1 was higher with HCV infection (3- to 5-fold) than with CCl4 treatment (1.5- to 2-fold), hinting that TINAGL1 plays a greater role in HCV-infected patients with liver fibrosis than in patients with fibrosis caused by other factors." (PMID 39781468, 2025).
liver fibrosis (continued). "Mechanistically, TINAGL1 directly binds to and stabilizes the known profibrotic factor PDGF-BB, which leads to the activation of HSCs and triggers liver fibrosis through the PDGF-BB/PDGFRβ signaling pathway." (PMID 39781468, 2025). "However, the role of TINAGL1 in liver fibrosis is still unknown." (PMID 39781468, 2025). "Mechanistically, TINAGL1 directly binds to and stabilizes PDGF-BB, leading to activation of HSCs and triggering liver fibrosis through the PDGF-BB/PDGFRβ signaling pathway." (PMID 39781468, 2025). "However, the expression did not increase further with the advancing fibrosis stage, and no significant gender differences in the expression of TINAGL1 were observed in the patients with liver fibrosis." (PMID 39781468, 2025).
liver steatosis (1 paper, 2025). "Consistently, overexpression of TINAGL1 in mice could not develop liver steatosis in CCl4-induced mice." (PMID 39781468, 2025). "However, the Oil Red O (ORO) staining results showed that overexpression of TINAGL1 in the mice could not develop liver steatosis during the treatment period." (PMID 39781468, 2025).
metastatic tumors (1 paper, 2024). "Intriguingly, the obtained results from our in vitro and ex vivo validation were in concordance with other studies that reported TINAGL1 as a Sec23a-dependent metastasis suppressor being upregulated in metastatic tumors." (PMID 38637790, 2024).
preeclampsia (1 paper, 2022). Preeclampsia is a hypertensive disorder of pregnancy that is characterized by new-onset hypertension with proteinuria presenting after 20 weeks of gestation, and depending on mild or severe forms may initially present with severe headache, visual disturbances, and hyperreflexia. "Two other proteins associated with the development of preeclampsia and affected by CHEM in this study are Tubulointerstitial nephritis antigen-like 1 (TINAGL1) and Endoplasmic Reticulum Aminopeptidase 2 (ERAP2)." (PMID 35406725, 2022).
soft tissue sarcoma (1 paper, 2024). A malignant neoplasm arising from muscle tissue, adipose tissue, blood vessels, fibrous tissue, or other supportive tissues excluding the bones. "Compared to non-metastatic patients, the GREM2 and CTSS genes exhibited significantly higher expression levels, while TINAGL1, ACKR1, and HLA-DRB1 showed a tendency to increase in metastatic soft tissue sarcoma (SS); however, these differences were not statistically significant." (PMID 39735532, 2024).
steatosis (1 paper, 2025). Increased lipid within the cytoplasm of cells. "Meanwhile, we found that the mRNA and protein levels of TINAGL1 were slightly increased in Hep G2 cells treated with free-fatty acid, hinting that TINAGL1 might serve as a factor in the pathogenesis of steatosis." (PMID 39781468, 2025).
tumor (10 papers, 2010 to 2025). "ZNF334 (p value < 0.0001) and TINAGL1 (p value < 0.0001) mRNA expression revealed a marked decrease in the lung of SCC tumor-bearing C57BL/6J compared to normal lung tissue and placebo-controlled." (PMID 38637790, 2024). "As the role of myCAFs in tumor progression is still not clearly understood, the correlation between TINAGL1 and CAF subtypes should be investigated in future studies." (PMID 38355577, 2024). "Taken together, stromal TINAGL1 expression was increased in tumor tissues of patients with DGC, and it can be an independent prognostic indicator for overall survival." (PMID 38355577, 2024). "Western blotting of paired normal and tumor tissues showed that the TINAGL1 protein levels were increased in tumor tissues." (PMID 38355577, 2024). "Among those selected, we investigated TINAGL1 as a potential drug target gene, because although TINAGL1 is regarded to be a tumor suppressor, in this study it was upregulated in a metastasis-enhanced cell line." (PMID 25521548, 2014). "Inhibition of TINAGL1 in CAFs slightly reduced tumor growth and volume." (PMID 38355577, 2024). "Inhibition of the TINAGL1/integrin/FAK axis can alleviate CAF-induced tumor progression in DGC." (PMID 38355577, 2024). "TINAGL1 expression in the TCGA-STAD dataset was also increased in DGC tumor tissues." (PMID 38355577, 2024). "We evaluated the role of CAF-secreted TINAGL1 in tumor progression and prognosis." (PMID 38355577, 2024). "The mRNA and protein levels of TINAGL1 and PDGF-BB were increased in the tumor tissues arising from HCV-eradicated Huh7.5 cells, in parallel with an increase of the tumor proliferative marker Ki67." (PMID 39781468, 2025). "RNA was extracted from tumor tissue, and the expression of DEIRGs including GREM2, CTSS, TINAGL1, ACKR1, HLA-DRB1, and STC2 was verified using real-time quantitative reverse transcription PCR (RT-qPCR)." (PMID 39735532, 2024). "The colocalization of TINAGL1 and COL1A1, a fibroblast marker, was observed and more pronounced in the tumor tissues." (PMID 38355577, 2024). "Notably, analysis of human specimens indicates an accumulation of TINAGL1+ CAFs in DGC tissues, establishing a significant correlation with tumor progression and oncologic outcomes." (PMID 38355577, 2024).